TNF (tumor necrosis factor)
Diseases named in the same sentence as TNF in open-access papers (continued):
Sharing a sentence is not in itself a finding about the gene and the disease.
depression (continued). "Increased pro-inflammatory markers [IL-6, IL-1β, TNF-α, and C-reactive protein (CRP)] occur in individuals with depression, supported by reports of anti-depressant effects of TNF-α antagonists." (PMID 35492581, 2022). "In conclusion, proinflammatory IL-1β and TNF-α showed to be more negatively correlated with white matter FA of the brain in outpatients with depression, particularly for IL-1β in the corpus callosum." (PMID 36261698, 2022). "It has been reported that patients suffering from depression present elevated serum levels of pro-inflammatory cytokines including interleukins, e.g., IL-1β, IL-6, and tumor necrosis factor-alpha (TNF-α)." (PMID 35740286, 2022). "Inflammatory factors such as interleukin (IL)-1, tumor necrosis factor (TNF)-a, nuclear factor-kappaB (NF-jB), and brain-derived neurotrophic factor (BDNF) have been implicated in the causative mechanism of depression." (PMID 35735405, 2022). "People with depression are characterized by increased levels of pro-inflammatory markers, such as interleukin (IL) IL-6, IL-1, tumor necrosis factor alpha (TNF-α) and C-reactive protein (CRP)." (PMID 36554751, 2022). "Of note, the correlations of TNF‐α and IL‐1β with depression were more obvious compared with IL‐6 and IL‐17." (PMID 34697903, 2022). "Patients with depression often show signs of inflammation, which was illustrated by the increased concentrations of cytokines such as IL-1, IL-6, and TNF-α in the peripheral blood and cerebrospinal fluid." (PMID 35411516, 2022). "BDNF, NPY, and TNF have been reported to be involved in the regulation of depression mediated by ELS, showing sex differences, too." (PMID 35663561, 2022). "Patients with depression have disrupted T-cell function and elevated levels of cytokines, such as tumor necrosis factor (TNF)-α, IL-1, and IL-6." (PMID 35850685, 2022). "For instance, an RCT revealed that psychotherapy simultaneously decreased depression scores and IL-6 and TNFα values, which were correlated with the social role component of one score." (PMID 36291336, 2022). "Researchers have observed high levels of pro-inflammatory cytokines including interleukin-1β (IL-1β), IL-6, and tumor necrosis factor-α (TNF-α) in the blood of patients suffering from depression and anxiety." (PMID 35242039, 2022). "While regular spiking (RS) cells show synaptic depression and exhibit TNF-α-dependent homeostatic recovery from depression, intrinsic bursting (IB) cells show potentiation that depends on CaMKII-autophosphorylation and not TNF-α." (PMID 35649371, 2022). "According to our previous review, IL-6, IFN-α, and TNF-α and CRP were associated with depression and anxiety." (PMID 35053845, 2022). "In this research, relatively stable markers, such as IL-6 and TNF-α, demonstrated enhanced and robust performance in predicting depression in patients with glioma." (PMID 35757220, 2022). "Meta-analyses have demonstrated that peoples suffering from depression have an increase in proinflammatory cytokines including tumor necrosis factor-α and interleukin-623." (PMID 36536111, 2022). "TNF-α (β = 0.263, p < 0.001), along with sleep quality (β = 0.27, p < 0.001) and depression (β = 0.376, p < 0.001), explained 42.7% of the variance in prenatal fatigue in the model." (PMID 36193420, 2022). "The difference mainly lies in the fact that the baseline TNF-α level was significantly lower in the HC group than in the patients with depression in either the active-rTMS or sham-rTMS groups." (PMID 35722555, 2022). "Prior evidence suggests that inflammatory cytokines (such as IL‐1β, IL‐6, and TNF‐α) are related to anxiety and depression in cancers, including colorectal cancer, breast cancer, and pancreatic cancer." (PMID 34697903, 2022). "Inflammatory signals are thought to play an important role in the development of depression and anxiety disorder, e.g., the cytokines IL-1β, IL-6, and TNFα." (PMID 35456304, 2022).
depression (continued). "The current study also revealed that serum TNF‐α, IL‐1β, IL‐6, and IL‐17 were positively correlated with anxiety and depression risks in NSCLC survivors." (PMID 34697903, 2022). "Research showed in rats that depression can lead to increased secretion of IL-1B and TNFα and reduced tear secretion." (PMID 35332110, 2022). "In children with obsessive compulsive disorder, significantly elevated levels of TNF-α and IL-12 were reported, while in adolescents with depression, the role of inflammation is being debated controversially." (PMID 36061277, 2022). "The concentrations of depression-related factors (5-HT and DA) and inflammatory factors (TNF-α, IL-6, and IL-1β) in the hippocampus and serum were assessed by ELISA assay." (PMID 36506556, 2022). "Fluoxetine, the main medication for the treatment of depression reduces the levels of IL-6 and TNF-α in patients." (PMID 36431060, 2022). "M1 macrophages preferentially produce many of the pro-inflammatory immune cytokines seen in depression, such as IL-6 and TNF-α, as well as pro-inflammatory nitric oxide (NO) and reactive oxygen species." (PMID 35977923, 2022). "This study found that the concentration of TNF-α in the depression group was significantly higher than that in the HC group, but there was no significant change after 2 and 12 weeks of antidepressant plus active or sham rTMS treatment." (PMID 35722555, 2022). "Beta-hydroxybutyrate (BHB), an endogenic NLRP3 inflammasome inhibitor, was shown to reduce depressive and anxiety behaviors in rodent models of depression and stress, potentially though decreasing hippocampal TNF-α concentrations." (PMID 35927237, 2022). "Our previous study suggested that elevated levels of TNF-α were related to poor executive function as measured using the Wisconsin Card Sorting Test (WCST) in patients with depressive disorder." (PMID 34637515, 2022). "The primary aim of this study was to compare the CSF levels of IL-6, IL-8 and TNF-α in geriatric patients with depressive disorders and an age- and sex matched control group." (PMID 36172507, 2022). "In general, antidepressant medications tend to reduce the levels of pro-inflammatory factors, such as TNF-α, IL-1β, and IL-6, found in many patients with depressive disorders." (PMID 35252227, 2022). "Reports consistently suggest that increased IL-6, TNF-α, and CRP levels are risk factors for mood and depressive disorders." (PMID 35558424, 2022). "Specifically, in this geriatric patient sample, we were not able to replicate previous findings of elevated CSF levels of inflammatory markers IL-6, IL-8 and TNF-α in patients with depressive disorders." (PMID 36172507, 2022). "In the same study, IL-6, TNF-α, IL-17a and IL-12p70 were elevated in the depression group on the third day after AMI compared to the control group." (PMID 36358455, 2022). "In the last few years, numerous studies further revealed that besides IFN-α, the proinflammatory cytokines IL-6 and TNF-α and increased blood levels of the C-reactive protein (CRP), in particular, are associated with depressive disorders." (PMID 36358455, 2022). "A meta-analysis from 2019 on children and adolescents with a diagnosis of depressive disorder included five studies and reported a trend for higher levels of TNF-α in participants with depressive disorders compared to controls." (PMID 35292108, 2022). "Since inflammation has been proposed to be a causative mechanism in the development of chronic stress-induced depression, we assessed the inflammatory cytokines TNF-α and IL-6." (PMID 34614119, 2021). "Meta-analyses have shown elevation of several cytokines such as TNF-alpha in patients with depression compared to healthy controls." (PMID 33805073, 2021). "Consistent with our results, several studies have shown the role of pro-inflammatory cytokines, particularly TNF-α, in diabetic neuropathy, depression, and learning and memory defects with inhibition of LTP." (PMID 33815140, 2021).
depression (continued). "In the present study, the levels of Il-6, TNFα, and corticosterone were quantified in the sera of LPS induced depression mice." (PMID 34790666, 2021). "Chang-Yu-Xiao-Yao-San can reduce the expression of inflammatory factors IL-6, IL-8, and TNF-α in the serum of patients with chronic hepatitis B combined with depression, and relieve the symptoms of depression in patients." (PMID 33790789, 2021). "Animal experimental results also show that Chang-Yu-Xiao-Yao-San inhibits an over-expression of serum IL-6, IL-8, and TNF-α in LPS-induced depression model rats and increased the content of hippocampal 5-HT in rats." (PMID 33790789, 2021). "A high level of interleukin-6 (IL-6) was predominantly observed in mania, tumor necrosis factor-α (TNF-α) was elevated in both depression and mania and C-reactive protein (CRP) level was even increased in euthymia." (PMID 34381386, 2021). "For example, mindfulness-based stress reduction (MBSR), CBT and supportive-expressive dynamic psychotherapy appear to reduce inflammatory markers (e.g., IL-6, TNF-α) in several diseases with comorbid depression." (PMID 33961667, 2021). "We also examined the effect of CSDS on PFC microglial cytokine expression, including IL‐1β, TNF‐α, and IL‐6, as those are reportedly increased in the cerebrospinal fluid and/or peripheral blood of patients with depression." (PMID 34043886, 2021). "A relevant meta-analysis showed that the concentrations of inflammatory factors such as IL-6 and TNF were higher than normal in patients with depression." (PMID 34257681, 2021). "For example, some rodent research reports showed that central and peripheral concentrations of inflammatory factors, especially IL-1 β, IL-6, and TNF-α, increased after the depression model was established by chronic unpredictable mild stress (CUMS)." (PMID 34531719, 2021). "TNF, dopamine, calcium signaling pathway, prolactin, and I-kappaB kinase/NF-kappaB signaling play important roles in the pathogenesis of depression." (PMID 34479552, 2021). "Increasing levels of proinflammatory mediators such as IL-1, IL-2, IL-6, and TNF-α have been observed in patients with depression." (PMID 33513891, 2021). "In people with MS with comorbid fatigue and/or depression, there are reported increased serum and CSF concentrations of the pro-inflammatory cytokines, such as interleukins (IL-1a, IL-1b, IL-2, IL-6), TNF-α and IFN-γ." (PMID 35242093, 2021). "In this study, we investigated the interaction between the inflammatory response system and depression, taking advantage of the measurement of the levels of the proinflammatory cytokine TNF-α in two cohorts of depressed patients." (PMID 34257748, 2021). "Subsequent Duncan’s post hoc test pointed out that the immunoneutralization of TNF-α mediated by Infliximab treatment restored the HFD diet-induced depression phenotype in mice." (PMID 34803583, 2021). "Proinflammatory cytokines, such as IL-1, interferon (IFN)-γ, TNF-α, etc., can lead to depression-like behavior and mood disorders by affecting synaptic plasticity." (PMID 34531719, 2021). "Conversely, anti-Tumor Necrosis Factor (TNF) therapies improve depression providing key empirical support for the “inflammatory theory” of depression." (PMID 32457424, 2021). "Chronic social defeat depression mouse model led to increased plasma levels of TNF-α in parallel with KYN, 3-HK, and KYNA as seen with IFNγ." (PMID 34072767, 2021). "Ketamine administration decreased the levels of IL-6, TNF-α, and IL-1β and suppressed the activation of NF-κB in depressed mice, suggesting pro-inflammatory inhibition plays an important role in depression treatment." (PMID 34772918, 2021). "The levels of interleukin-1 beta (IL-1β), interleukin-6 (IL-6), and tumor necrosis factor alpha (TNF-α) in the serum of patients with depression are also significantly higher than those of normal people." (PMID 33790789, 2021).
depression (continued). "Elevation in plasma TNF levels is believed to play the role of a mediator in patients with depression compared with healthy individuals." (PMID 33920992, 2021). "A total of 56 signaling pathways (P < 0.05) were identified by Kyoto Encyclopedia of Genes and Genomes analysis, mainly involving depression-related pathways such as dopaminergic synapse, TNF signaling pathway, and prolactin signaling pathway." (PMID 34479552, 2021). "TNF-α was not only found to be increased in patients with depression but was also shown to induce depressive symptoms if injected directly; such symptoms improved after administration of anti-TNF-α agents." (PMID 33578686, 2021). "In people with MS and comorbid fatigue and/or depression there is reported increased serum and cerebrospinal fluid concentration of inflammatory mediators such as tumor necrosis factor, interleukins (IL-1a, IL-1b, IL-6), interferon γ and neopterin." (PMID 35242093, 2021). "Younger adults suffering from depression present a significant decrease in the peripheral levels of IL-6, TNF-α, IL-10, and MCP1 after pharmacological treatment with antidepressants." (PMID 35002817, 2021). "A 2 year South Korean longitudinal study presented various correlations between five proinflammatory cytokine levels (TNF-α, IL-1α, IL-1β, IL-6, and IL-8) and late-life depression (LLD) from cross-sectional and prospective perspectives." (PMID 34299040, 2021). "It is worthy to mention data from two clinical trials, based on biologic therapy, and in particular that using infliximab which is a chimeric IgG1 mAb that blocks TNF-α for the treatment of refractory depression." (PMID 34367160, 2021). "Especially with regard to CSF WBC the results are surprising since CSF inflammatory markers such as TNF-α and IL-1β measured in the cerebrospinal fluid of treatment-naive MS patients correlate with depression scores." (PMID 34764926, 2021). "Previous meta-analysis noted an increase in proinflammatory cytokines (TNFα and IL-6) in people with depression." (PMID 33919670, 2021). "As with other publications on TNF-α levels in depression, limitations of our study mainly arise from the relatively small study cohort." (PMID 34257748, 2021). "Patients with depression showed increased levels of IL-8, IL-10, IL-12, and IL-13, whereas IL-6 and TNF-α showed mixed results between studies." (PMID 33578686, 2021). "Depression is also considered to be related to inflammation, and EA was found to decrease both IL-1β and TNF-α expression, which was also found to alleviate leptin resistance and relieve depression." (PMID 34281592, 2021). "In particular, numerous studies reported that TNF-α levels are elevated in patients with major depression and bipolar disorder." (PMID 33921721, 2021). "The colon levels of IL-6, IL-1β, and TNF-α in the depression model group was significantly increased (p < 0.01; F = 19.265, F = 38.3, and F = 57.968, respectively) compared with the control group." (PMID 33505499, 2021). "Several clinical trials attested for the antidepressant efficacy of anti-TNF-α compounds (in patients with medical illnesses, major depression, or bipolar depression)." (PMID 33921721, 2021). "Reduce the expression of cytokines IL-1β, IL-6, TNF-α, and improve depression-like behavior in CUMS rats." (PMID 35185541, 2021). "Inflammatory cytokines like IL-6 and TNF-α are involved in the pathogenesis of depression and have been found to increase in previous animal models of depression and in patients with clinical depression." (PMID 33987106, 2021). "NE acts on microglia and regulates the release of inflammatory factors such as interleukin 6 (IL‐6), interleukin 1β (IL‐1β), and tumor necrosis factor α (TNF‐α); therefore, NE regulates neuroinflammation, neuropathic pain, anxiety, and depression." (PMID 37786561, 2021). "The imipramine and fluoxetine also reduced the production of TNF-α both in human patients and in the animal model of depression." (PMID 33628324, 2021).
depression (continued). "For example, LPS administration at 30 days post-TBI exacerbated cognitive impairment and induced depression-like behavior, both of which were associated with microglial reactivation and an exaggerated production of pro-inflammatory cytokines IL1-β and TNFα." (PMID 34944762, 2021). "Antibodies targeting TNF-α, Infliximab, and Golimumab, have been investigated in several clinical trials in patients with major depression." (PMID 33746786, 2021). "Specifically, IL-6 and TNF-α have been identified as the only two cytokines that are consistently elevated in diagnosed major depression." (PMID 34589733, 2021). "Reserpine, which induces anxiety and depression, increased levels of proinflammatory cytokines, TNF-α, IL-6, IL-12, and IFN-γ, mRNA, which induce inflammation and regulate immune cells in serum." (PMID 34220460, 2021). "Demonstrated in some studies is the long-lasting increased level of such cytokines as, for example, IL-6, IL-1β and TNF-α, which means a longer exposure to factors contributing to the development of depression." (PMID 34575258, 2021). "The control of inflammation by α7 nAChR has been linked to depression, as knock-out mice for α7 nAChR were observed to develop a depression-like phenotype and exhibit high levels of TNF-α and IL-1β." (PMID 34948222, 2021). "After treatment with venlafaxine, the level of TNF-α in patients with depression decreased significantly, and the level of TNF-α in the effective group decreased more." (PMID 33582959, 2021). "Increased TNF-α, one of the most important proinflammatory cytokines families, has been reported in clinical depression." (PMID 34358084, 2021). "Another mediator of inflammation that plays a significant role in the pathogenesis of depression is TNF-α, which is produced in small amounts by neurons and microglia." (PMID 33920992, 2021). "Depression displays strong relation to an increase in peripheral inflammatory mediators, such as IL-6, C-reactive protein and TNF-α." (PMID 34200513, 2021). "We found that LPS administration induced significant elevation of TNF-α, IL-1β, and IL-6 inflammatory cytokines levels, while these have been reported to contribute to the pathogenesis of depression." (PMID 34207497, 2021). "Ketamine, which has demonstrated efficacy in cases of chronic, treatment-resistant depression, exhibits a broad spectrum of anti-inflammatory effects (e.g., TNFα and IL-6 inhibition) in both clinical and preclinical studies." (PMID 33935636, 2021). "This study showed that dietary CAP improved depressive-like behavior (sucrose preference test, forced swimming test, tail suspension test) and levels of 5-HT and TNF-α in serum of LPS-induced mice with depression-like behaviors." (PMID 33987106, 2021). "Several studies have further found that the hippocampal concentrations of the pro-inflammatory cytokines IL-6, IL-1β, and TNF-α are elevated in mice with depression-like behavior." (PMID 34220460, 2021). "Following this, increased TNF-α and IL-1β were released into brain, inducing neuroinflammation and finally depression-like behaviors." (PMID 34827513, 2021). "A meta-analysis showed that patients with major depressive disorder had higher levels of plasma IL-6, TNF-α, and soluble interleukin-2 receptors (sIL-2R)." (PMID 34295268, 2021). "IL-6 and TNF-α have been reported to be elevated in mice showing behavioral despair and in patients with depression." (PMID 34040528, 2021). "In a prospective cohort study of 183 enrolled patients with IBD, treatment with anti-TNF agents or vedolizumab resulted in improvement of depression, sleep and anxiety within 6 weeks of initiation of treatment up until one year or more." (PMID 33498197, 2021). "It has been shown that the levels of pro-inflammatory cytokines, mainly the interleukins (IL), such as, IL-1, IL-6, IFN-γ, and TNF-α, are elevated in the serum of patients suffering from depression." (PMID 34248517, 2021).